ATG5 (autophagy related 5)
Diseases named in the same sentence as ATG5 in open-access papers (continued):
Sharing a sentence is not in itself a finding about the gene and the disease.
heart failure (12 papers, 2010 to 2024). Inability of the heart to pump blood at an adequate rate to meet tissue metabolic requirements. "Recent reports have indicated that cardiomyocyte-specific Atg5-deficient mice develop left ventricular hypertrophy that progresses to heart failure, which ultimately leads to premature death." (PMID 39931517, 2024). "Third, Nox2 deficiency prevents the increases in LC3 II, Beclin1 and Atg5-Atg12 protein expression and reduces myocyte apoptosis and myocardial fibrosis in doxorubicin-induced heart failure." (PMID 38521855, 2024). "Loss of autophagy-related 5 (ATG5), a key protein in autophagy, causes heart failure in diabetic cardiomyopathy, whereas the enhancement of autophagy can delay the progress of hypoxic heart disease and improve ventricular remodeling." (PMID 32655948, 2020). "However, Atg5-deficient animals developed contractile dysfunction and heart failure accompanied by increased levels of ubiquitinated proteins." (PMID 20937113, 2010). "According to the results from our study, the combination of Met with GS significantly prevented the increase in the ratio of LC3-II to LC3-I in heart failure mice, reduced the expression of the autophagy markers Beclin 1 and Atg5, and reversed the decrease in the p62 protein." (PMID 39141645, 2024). "Furthermore, ANP mRNA expression, a heart failure biomarker, increased in DOX-treated hearts and was inhibited when ATG5 was knocked down by rAAV9-shRNA-ATG5." (PMID 39931517, 2024). "Starvation of newborn mice lacking atg5 increases perinatal death resulting from heart failure, suggesting that the heart function critically relies on autophagy during nutrient starvation." (PMID 26741505, 2016).
pancreatitis (12 papers, 2014 to 2025). Inflammation of the pancreas. "However, in another study, knocking out Atg5 in the pancreas of mice caused spontaneous pancreatitis, similar to knocking out Atg7." (PMID 38605381, 2024). "In addition, we and others have shown that genetic intervention leading to the local removal of essential autophagy genes such as autophagy-related 5 and 7, Atg5, Atg7, or lysosomal-associated membrane protein-2 (Lamp2) promotes the development of pancreatitis in rodents." (PMID 33087696, 2020). "Consistently, it has been reported that disruption of autophagy by depletion of ATG5 or ATG7, as well as impairment of lysosomal function, is sufficient to cause spontaneous pancreatitis in mice." (PMID 40577485, 2025). "An experiment in a pancreatitis model which was constructed in ATG5 knockout mice reported that autophagy was activated in these animals resulting in a reduction in the severity of pancreatitis." (PMID 38358010, 2024). "Knockout of the essential autophagy gene, Atg5, in the mouse pancreas blocked acinar cell autophagy and reduced caerulein-induced pancreatitis, implicating autophagy in pancreatitis-induced tissue damage." (PMID 35159064, 2022). "Genetic ablation of Atg5 or TFEB specifically in mouse pancreatic acinar cells induced fibrotic pancreatitis in mice fed with either Gao-binge alcohol or liquid control diet." (PMID 31987928, 2020). "Among the adaptive responses, autophagy plays a critical role to maintain the homeostasis of acinar cell function, as the whole pancreas deletion of Atg5 led to the development of spontaneous pancreatitis." (PMID 31987928, 2020). "We have shown that human pancreatitis is associated with disabled autophagic ATG7 and ATG5, as well as a reduction of LAMP2 protein expression, impairing acinar cell autophagy signaling." (PMID 33087696, 2020). "Together, these data indicate that genetic deletion of Atg5 in acinar cells promotes the fibrotic pancreatitis after the mice were fed with the Lieber-Decarli liquid diet regardless of ethanol feeding, which is similar to TFEB KO mice." (PMID 31987928, 2020). "In a mouse model of pancreatitis, autophagy repressed by deletion of Atg5 dysregulated TBK1 signaling and upregulated PD-L1." (PMID 31627272, 2019). "While a high-fat diet has been associated to pancreatitis, a Western diet that contains more than 40% fat did not cause more injury in these acinar cell–specific Atg5 or TFEB KO mice (data not shown)." (PMID 31987928, 2020). "Nevertheless, an early study using pancreas acinar cell-specific-Atg5 KO mice showed decreased acinar cell vacuolization and pancreatitis after cerulein treatment, and the authors proposed that autophagy machinery may be required for the trypsinogen activation to induce pancreatitis." (PMID 25140315, 2014). "It has also been shown that defective hepatic autophagy promotes ER stress in obese mice and constitutive pancreatitis and ER stress in pancreas specific ATG7 and ATG5 mice." (PMID 37749555, 2023). "Acinar cell-specific Atg5 KO and acinar cell-specific TFEB KO mice developed severe inflammatory and fibrotic pancreatitis in both Gao-binge alcohol and control diet-fed mice." (PMID 31987928, 2020). "However, Atg5 mainly regulates the upstream formation of autophagosomes, and it is possible that upstream autophagy (autophagosome biogenesis) and downstream of autophagy (autolysosome degradation) could play different roles in pancreatitis." (PMID 25140315, 2014). "Pancreatic acinar cell–specific depletion of ATG5 or TFEB in the mouse developed fibrotic pancreatitis regardless of alcohol feeding." (PMID 31987928, 2020).
Alzheimer disease (11 papers, 2015 to 2025). A progressive, neurodegenerative disease characterized by loss of function and death of nerve cells in several areas of the brain leading to loss of cognitive function such as memory and language. "In the study about susceptibility of Alzheimer’s disease, plasma levels of ATG5 were significantly elevated in patients with dementia or mild cognitive impairment compared with the control participants." (PMID 34661876, 2022). "Altered levels of ATG5 have been associated with human diseases, including multiple sclerosis, Alzheimer's disease, and cancers." (PMID 32377431, 2020). "BACE1-AS could also enhance autophagy-related neuronal damage via the miR-214-3p/ATG5 signaling axis in Alzheimer's disease." (PMID 34970559, 2021). "Increased BACE1-AS showed enhanced autophagy in Alzheimer disease by targeting miR-214-3p, Beclin-1, LC3-I/LC3-II, p62, and ATG5." (PMID 38461204, 2024). "Recently, the involvement of a novel form of noncanonical autophagy that is facilitated by autophagy proteins, including Atg5, LC3, Atg16L, and Rubicon, was identified during endocytosis of amyloid beta (Aβ) in a mouse model of Alzheimer’s disease (AD)." (PMID 33854187, 2021). "In the present study, we show that IDN5706 disrupts APP glycosylation, and stimulates the degradation of iAPP through Atg5-dependent autophagy, with a resulting reduction in the processing of APP to CTFs, which could have beneficial effects to Alzheimer's disease." (PMID 26308941, 2015).
autoimmune disease (11 papers, 2017 to 2023). A disorder resulting from loss of function or tissue destruction of an organ or multiple organs, arising from humoral or cellular immune responses of the individual to their own tissue constituents. "Second, the pathogenic association between elevation in tear ATG5 and SS has not been fully understood, although the pathogenic implication of autophagy in autoimmune disease including SS has been reported." (PMID 33406739, 2021). "Studies have also shown that ATG5 gene may act as a potential risk factor to promote the occurrence of autoimmune diseases." (PMID 35518570, 2022). "Since most autoimmune diseases have similar pathogenesis and are related to various common genetic variations, we proposed a hypothesis that some ATG5 polymorphisms might be genetic factors correlated with potential AITDs." (PMID 35518570, 2022). "Association of ATG5 with different diseases suggests a pleiotropic role of ATG5 in many physiological processes and a potentially shared pathomechanism underlying these diseases, which include neurodegenerative diseases, autoimmune diseases, and inflammatory diseases." (PMID 29326554, 2017). "Apoptosis is implicated in the pathogenesis of several autoimmune diseases, and thus we cannot rule out that the association of ATG5 with certain diseases is solely linked with autophagy or apoptosis." (PMID 30386331, 2018). "Further research is needed to determine whether apoptosis plays a role in ATG5-induced autoimmune diseases." (PMID 30386331, 2018). "Given the multi-faced function of ATG5, it is reasonable to speculate that it might be involved with other diseases whose pathogenesis interferes with autophagy or apoptosis; for example, the large spectrum of autoimmune diseases." (PMID 30386331, 2018). "The results of GWAS studies, as well as custom SNP genotyping array targeting autoimmune disease loci, have shown enrolment of apoptotic genes, for instance, the DNASE1L3 gene and genes related to autophagy, such as autophagy-related 5 gene (ATG5) in SSc." (PMID 37446389, 2023). "Thus, a deeper understanding of ATG5's role in the autophagy mechanism may shed light on the link between autophagy and the immune response, and lead to the development of new therapies for autoimmune diseases and autoinflammatory diseases." (PMID 30386331, 2018).
steatosis (11 papers, 2014 to 2022). Increased lipid within the cytoplasm of cells. "Similar to autophagy deficiency in hepatocytes, our study demonstrates that Atg5 deletion in hepatic CD11c+ cells contributes to the development of hepatomegaly, steatosis, and progression to NAFLD." (PMID 35301333, 2022). "Explanted livers from Atg5 CD11cKO mice were pale and twice as heavy as control livers, highlighting the development of hepatomegaly and suggesting steatosis." (PMID 35301333, 2022). "After comparison between the two groups, we identified that Atg5 CD11cKO mice had more steatosis, ballooning, and lobular inflammation compared to WT mice resulting in an increased NAS score." (PMID 35301333, 2022). "Gene expression of autophagy-like proteins was higher in the disease states: ATG7 was higher in NASH in comparison to HC, and ATG5 was higher in steatosis when compared to HOC." (PMID 34869521, 2021). "In our study, empagliflozin treatment led to activation of autophagy in both db/db mice and a hepatocyte steatosis model, based on alterations of autophagy markers including p62, Beclin-1, and ATG5." (PMID 33551821, 2020). "Immunofluorescence and western blot results showed that under PA and HG-induced steatosis, cellular levels of ATG5 and Beclin-1 were decreased, and p62 was increased." (PMID 33551821, 2020). "In contrast, Compound C decreased the levels of TET2, ATG5, and Beclin-1 and increased p62 in the hepatocyte steatosis model." (PMID 33551821, 2020). "Thus, peretinoin enhanced autophagy by increasing Atg5-Atg12-Atg16L1 pathway activation and reduced steatosis, inflammation, and tumorigenesis in 2 different NASH-HCC mouse models." (PMID 28591717, 2017). "Although Pten-deficient livers develop steatosis and HCC, we observed that hepatic Pten deletion alone did not initiate liver damage, inflammation, hepatic stellate cell activation, fibrosis, or a ductular reaction in young livers, but these effects were observed on hepatic deletion of ATG5 or ATG7." (PMID 34088666, 2021). "Histological analysis was conducted to evaluate steatosis, ballooning, lobular inflammation, and NAS of control and Atg5 CD11cKO mice." (PMID 35301333, 2022). "For the “ferroptosis” pathway three genes were higher (FTL, ATG5, and MAP1C3A) and two were lower in steatosis (SLC40A1 and MAP1LC3C)." (PMID 34869521, 2021). "Within fasting-induced steatosis models, we analyzed 11 experiments from 10 manuscripts that used genetic liver-specific KO models for ATG7, ATG5, TFEB, and FIP200." (PMID 33937257, 2021). "Importantly, on histological examination, we observed that anti-IL-23 treatment prevented the development of steatosis, ballooning, lobular inflammation, and reduced NAFLD scores in Atg5 CD11cKO mice when compared to isotype controls." (PMID 35301333, 2022). "Also, under the depletion of TET2, autophagy was no longer activated by empagliflozin in the hepatocyte steatosis model, based on the levels of Beclin-1, ATG5, and p62." (PMID 33551821, 2020). "Acute alcohol binge exacerbated injury and steatosis in Atg5-deleted but not Atg7-deleted livers." (PMID 31614437, 2019).
glomerulopathy (10 papers, 2013 to 2024). "For example, streptozotocin‐induced chronic hyperglycemia leads to glomerulopathy, whose phenotypic manifestation is more severe in Atg5‐deficient podocytes than their wild‐type counterparts." (PMID 34459017, 2021). "On the contrary, studies have shown that there is an increased susceptibility to glomerular disease following loss of Atg5." (PMID 29725042, 2018). "For example, a study on in vivo animals confirmed that podocyte-specific deletion of autophagy-related 5 (Atg5) exhibited strongly increased susceptibility to models of glomerular disease, highlighting the importance of induced autophagy as a key homeostatic mechanism to maintain podocyte integrity." (PMID 39850100, 2024). "This study confirmed for the first time that podocyte-specific deletion of autophagy-related 5 (Atg5) exhibited strongly increased susceptibility to models of glomerular disease, highlighting the importance of induced autophagy as a key homeostatic mechanism to maintain podocyte integrity." (PMID 39850100, 2024). "Specific ablation of autophagy gene Atg5 result in albuminuria and glomerulopathy in aging mice and podocyte deletion of Atg7 exaggerate ADR-induced podocyte injury." (PMID 34580283, 2021). "Deletion of Atg5 in podocytes led to glomerulopathy as well as ER stress and proteinuria in aging mice." (PMID 29725042, 2018). "The podocyte-specific Atg5 knockout mice develop glomerulopathy gradually during aging." (PMID 30654583, 2019). "The podocyte-specific depletion of the Atg5 gene leads to glomerulopathy in aging mice, whose oxidative and ubiquitinated protein accumulation and podocyte endoplasmic reticulum stress eventually lead to loss of podocytes, increased proteinuria, and glomerulosclerosis." (PMID 30654583, 2019). "Greatly increased susceptibility to glomerular disease was exhibited in mice lacking Atg5 gene in podocytes." (PMID 27077005, 2016).
lung adenocarcinoma (10 papers, 2014 to 2022). A carcinoma that arises from the lung and is characterized by the presence of malignant glandular epithelial cells. "To investigate the effect of stable autophagy inhibition in RAS-mutated human cancer cells, we used CRISPR/Cas9 to ablate ATG5 expression in A549 lung adenocarcinoma cells." (PMID 29146913, 2017). "The migration and invasion of lung adenocarcinoma cells promoted by miR-106a were significantly attenuated by Atg5 short hairpin RNA or 3-MA, which indicated that the pro-metastatic role of miR-106a was partially dependent on autophagy." (PMID 34718338, 2021). "The expression of ATG5 and Zeb1 were both positively correlated with the stage of human lung adenocarcinoma." (PMID 33468994, 2021). "In summary, ATG5 rs510532 and ATG10 rs10036653 genetic variations in autophagy core genes are significantly associated with clinical outcomes of advanced lung adenocarcinoma treated with gefitinib." (PMID 29259263, 2017). "Co-treatment with troglitazone, TRAIL, and ATG5 siRNA strongly increased cell viability in human lung adenocarcinoma A549 cells with significantly decreased cell death." (PMID 28460464, 2017). "In addition, the expression of ATG5 was also positively correlated with the expression of Zeb1 in human lung adenocarcinoma." (PMID 33468994, 2021). "In lung adenocarcinoma, lncRNA KCNQ1OT1 was also reported to upregulated radioresistance via miR-372-3p/ATG5 and ATG12 axis." (PMID 35600868, 2022). "Among lung adenocarcinoma patients with EGFR-mutant, ATG5 rs510432 have been proved to contribute to disease prognosis." (PMID 34661876, 2022). "We found that ATG5 rs510532 and ATG10 rs10036653 contributed to not only survival but also drug resistance among gefitinib-treated advanced lung adenocarcinoma patients." (PMID 29259263, 2017). "In this study, hinokitiol induced autophagy, but not apoptosis or necrosis, in lung adenocarcinoma cells in vitro and in vivo, as demonstrated by LC3, ATG5, and p62 expression and AVO formation measurements." (PMID 25105411, 2014).
multiple myeloma (10 papers, 2014 to 2025). "TRIM21 has been found to target ATG5 and mediate K48-linked ATG5 ubiquitination and degradation to block pro-survival autophagy in multiple myeloma cells." (PMID 40735642, 2025). "An intron SNP in the ATG5 gene (rs9372120) has been associated to multiple myeloma by a genome-wide association study." (PMID 32377431, 2020). "Bortezomib treatment of myeloma cells lead to ATG5 cleavage through a calpain-dependent manner while calpain inhibition or a calpain-insensitive Atg5 mutant promoted bortezomib-resistance." (PMID 25481044, 2014). "Bortezomib treatment of myeloma cells generated the truncated 24 kDa form of ATG5 as seen by western blot." (PMID 25481044, 2014). "In multiple myeloma cell lines, pharmacologic or genetic inhibition by knockdown of Beclin-1 or Atg5, augments doxorubicin-induced cell death." (PMID 24970805, 2014). "Myeloma cells were also transfected plasmids that expressed either Atg5-WT or an Atg5-T193G-T194G, a calpain-resistant ATG5 mutant." (PMID 25481044, 2014). "Furthermore, pharmacologic or genetic inhibition of autophagy by knockdown of Beclin-1 or Atg5 expression augments doxorubicin-induced cell death in multiple myeloma cell lines." (PMID 28208617, 2017). "For example, TRIM21 is involved in degradation of cyclin-dependent kinase 2 (CDK2) and ATG5 in AML and multiple myeloma cells." (PMID 40371639, 2025). "Myeloma cells were transfected with a plasmid that expressed FLAG-Bcl2, treated with bortezomib and AICAR as indicated, lysates prepared and immunoprecipitated and probed with an ATG5 antibody." (PMID 25481044, 2014).
adenoma (9 papers, 2012 to 2024). A neoplasm arising from the epithelium. "Subsequent studies demonstrated that Atg5-/- and Atg7-/- livers give rise to adenomas, Atg4C-/- mice are susceptible to chemical carcinogenesis, and Bif1-/- mice are prone to spontaneous tumors, indicating that autophagy defects promote tumorigenesis." (PMID 23181220, 2012). "Loss of Atg5 (autophagy related 5) or Atg7 in the mouse liver is associated with damaged mitochondria and peroxisomes, lipid droplets and accumulation of protein aggregates with p62 and Keap1, leading to sustained Nrf2 activation that causes benign adenoma." (PMID 34206503, 2021). "Consistently, loss of p62 in ATG5 or ATG7-depleted mouse models were found to suppress tumor growth, suggesting there is a correlation between p62 accumulation and adenoma formation." (PMID 39178313, 2024). "Mechanistically, it has been reported that heterozygous deletion of ATG5 activated EGFR and Wnt/β–catenin pathways in adenomas of Apc(Min/+) mice leading to the enhancement of the IFN γ-dependent inhibition of these pathways." (PMID 33809172, 2021). "Interestingly, interferon-gamma has revealed a strong inhibition effect on adenomas of ApcMin/+ATG5+/−mice without obvious side effects." (PMID 30374741, 2018).